TIMP1 (TIMP metallopeptidase inhibitor 1)
Diseases named in the same sentence as TIMP1 in open-access papers (continued):
Sharing a sentence is not in itself a finding about the gene and the disease.
lymph node metastasis (17 papers, 1998 to 2025). "TIMP1-high expression significantly correlated to invasive clinical features, including lymph node metastases and higher risk stratification." (PMID 38770133, 2024). "The results showed that elevated TIMP-1 levels were significantly associated with lymph node metastasis (N1/N2/N3 vs N0, OR = 2.92, 95% CI [1.95–4.38]) and higher TNM stages (III/IV vs I/II, OR = 2.73, 95% CI [1.23–6.04])." (PMID 33628641, 2021). "TIMP1 was found to be a sensitive biomarker in patients with metastatic colon cancer, and higher TIMP1 levels were linked to lymph node metastases, vascular invasion and distant metastasis in CRC patients." (PMID 35003085, 2021). "TIMP1 level increases in CRC have been associated with lymph node metastasis, distant metastasis, and vascular invasion, and TIMP1 mediation of the AK-PI3K/AKT and MAPK pathways may be involved in inhibiting proliferation, metastasis, and increased apoptosis." (PMID 33579281, 2021). "Moreover, clinicopathological parameter data analysis showed that elevated TIMP-1 levels were significantly associated with lymph node metastasis (N1/N2/N3 vs N0: OR = 2.92, 95% CI [1.95–4.38]) and higher TNM stages (III/IV vs I/II: OR = 2.73, 95% CI [1.23–6.04])." (PMID 33628641, 2021). "Univariate analysis identified TIMP1 expression (p = 0.004), lymph node metastasis (p = 0.019), and distant metastasis (p < 0.001) as significant factors influencing five-year overall survival." (PMID 41511313, 2025). "TIMP1 was found to be overexpressed in colon tissue and lymph node metastasis specimens, and suppression of TIMP1 expression inhibited proliferation, and metastasis but promote apoptosis through inducing FAK-PI3K/AKT and MAPK pathway." (PMID 36991138, 2023). "Of the 36 samples of available lymph node metastasis specimens, 29 samples (80.6 %) showed TIMP1 overexpression." (PMID 27644693, 2016). "Within this group of proteases, only MMP9, MMP13, MMP14, and TIMP1 have correlated with depth of tumoral invasion, lymph node metastasis, and an unfavorable prognosis in GC patients." (PMID 24669030, 2014). "High levels of MMP-13 in these two tissue compartments were strongly correlated with each other, and further correlated with Her-2/neu, TIMP-1, lymph node metastasis and decreased overall survival." (PMID 18373849, 2008). "Further operating characteristic curve (ROC) analysis of TIMP-1 showed that its staining scores could discriminate between primary tumor and lymph node metastasis (area under the curve, 0.809; 95% CI, 0.649 to 0.969)." (PMID 28030805, 2017). "The significant correlation between TIMP-1 expression and the presence of lymph node metastases, as well as that between TIMP-1 plasma concentration and stage of cancer histological differentiation, might indicate the importance of this molecule as a prognostic factor during carcinogenesis." (PMID 31143300, 2019).
osteosarcoma (17 papers, 2004 to 2025). A usually aggressive malignant bone-forming mesenchymal neoplasm, predominantly affecting adolescents and young adults. "For example, adding recombinant TIMP-1 to osteosarcoma cells activated RAS via phosphorylation of RAF1." (PMID 41002380, 2025). "In osteosarcoma cells TIMP-1 has a dual influence on tumor progression; either beneficial by impairing angiogenesis or detrimental by favoring cancer cells growth or survival." (PMID 31195680, 2019). "For example, increased expression of MMP-9 has been found to correlate with osteosarcoma metastasis in patients and inhibitors of MMPs, such as TIMP-1 have been shown to inhibit invasiveness of osteosarcoma tumor cells in vitro." (PMID 24190483, 2014). "In osteosarcoma, piperine inhibited cell migration by reducing the expression of MMP2 and MMP9 and increasing the expression of TIMP1 and TIMP2." (PMID 36678600, 2023). "Proliferation, migration, cell cycle analysis and expression in osteosarcoma cell lines of matrix metalloproteinases such as gelatinases MMP-2 and MMP-9 and their inhibitors TIMP-1 and TIMP-2 were studied." (PMID 26959001, 2016). "Interaction between TIMP1 and αvβ3 confers protection against apoptosis induced by TNF-α In human osteosarcoma cell lines." (PMID 23522389, 2013). "Additionally, in osteosarcoma cells, it also possesses the anti-metastatic activity by down-regulating the MMP-2 and MMP-9 secretions and increasing the TIMP-1 and TIMP-2 expressions via Akt-dependent and p38 pathways." (PMID 34068885, 2021).
cervical carcinoma (16 papers, 2004 to 2025). A carcinoma arising from either the exocervical squamous epithelium or the endocervical glandular epithelium. "To investigate if Sdc-1 in its different forms influences the expression of invasion-related factors, we analyzed the expression levels of E-cad, MMP2, and tissue inhibitor of metalloproteinases 1 (TIMP-1), which are also associated with the metastasis of cervical cancer cells by qRT-PCR." (PMID 35155241, 2022). "Various findings demonstrate the potent anti-invasion activity of TIMP-1 by inhibiting MMP in the cervical cancer HeLa cell line by cannabinoid THC." (PMID 40008130, 2025). "Further analysis revealed that MMP14, 23B and 25 were located in significant genomic amplification regions and MMP1, 15, 17 and TIMP1 in all our 6 cervical cancer cell lines." (PMID 29312578, 2017). "After treating with IL-17A, the expression of MMP2 and MMP9 proteins in cervical cancer cell lines (C33A and Caski) was increased, meanwhile the expression of TIMP-1 and TIMP-2 proteins was decreased." (PMID 25250801, 2014). "This study aimed to assess whether the expression of MMP-2, MMP-9, MMP-14, TIMP-1, and TIMP-2 in tumors and in the adjacent stroma is associated with cervical cancer prognosis." (PMID 32669083, 2020). "Interestingly, MMP9 and MMP2 up-regulation in cervical cancer was previously reported and the combined overexpression of MMP9, MMP11 and TIMP1 has been associated with the invasive features of some cancers." (PMID 15989693, 2005). "Upregulation of TIMP-1 forms the MMP-9 and MMP-2, which are inhibitory complexes that initiate anti-invasion of cervical cancer." (PMID 40008130, 2025). "Piperine has been shown to regulate MMP2, MMP9, TIMP1, and TIMP2 in cervical cancer cells at the gene and protein levels." (PMID 36678600, 2023). "IL-17A could promote the migration and invasion of cervical cancer cell via up-regulating MMP2 and MMP9 expression, and down-regulating TIMP-1 and TIMP-2 expression via p38/NF-κB signal pathway." (PMID 25250801, 2014).
lung disease (16 papers, 2009 to 2024). "Disruption of the balance between MMP-9 and endogenous inhibitors (including TIMP-1, also described as protease/antiprotease imbalance) has been implicated in the pathology of these pulmonary diseases." (PMID 26264019, 2015). "A high MMP9/TIMP1 ratio has been shown to be associated with a less severe progression of different lung diseases." (PMID 21547259, 2011). "An increase in the MMP-9/TIMP-1 ratio was also associated with the severity of lung disease and could indicate airway inflammation and bronchial injury while causing clinical differences in chronic airway diseases." (PMID 37509076, 2023). "High TIMP-1 expression is associated with severe lung disease." (PMID 21547259, 2011). "In this regard, it is remarkable that even clinical stable CF patients with mild pulmonary disease revealed an imbalance of the MMP-9/TIMP-1 ratio in BAL indicating the contribution of the proteases in the chronic inflammatory process in CF lung disease." (PMID 26185365, 2015). "Notably, one study has found that exercise can attenuate pulmonary disease by regulating TIMP1 expression." (PMID 38956886, 2024). "Liver and pancreas represent two other organ systems that are, apart from the lung, frequently affected by CF and thus might act as potential confounders of the observed up-regulation of MMP-8, MMP-9, YKL-40 and TIMP-1 in CF lung disease." (PMID 25545245, 2014). "Together with the elevated TIMP-1/2 concentrations observed at 6 months, this may indicate that tissue remodelling continues which may be one reason that some patients develop fibrotic lung disease following infection." (PMID 23613834, 2013). "On the other side, TIMP‐1 plays a critical role in ECM turnover and lung remodeling during the development of pulmonary diseases." (PMID 39267201, 2024). "Adults and children with moderate to severe CF lung disease exhibited significantly increased serum expression of MMP-8, MMP-9, YKL-40 and TIMP-1." (PMID 25545245, 2014). "Although the expression of TIMP‐1 by macrophages is increased in some lung diseases but decreased in other lung diseases, the contributions of TIMP‐1 to the macrophage function are not known but will be the focus of our future studies." (PMID 33656791, 2021).
metabolic syndrome (16 papers, 2010 to 2025). A cluster of metabolic risk factors for CARDIOVASCULAR DISEASES and TYPE 2 DIABETES MELLITUS. "Compared with these studies, our results by stratifying obese population into different groups based on BMI and metabolic syndrome status further investigate TIMP-1 levels." (PMID 34625635, 2021). "We also showed that individuals with metabolic syndrome have a higher level of TIMP1 and similar results were reported elsewhere." (PMID 31178745, 2019). "Moreover, increased plasma concentrations of MMP8 and TIMP1 (along other pro-inflammatory cytokines) have been previously reported in patients with features of the metabolic syndrome (MeS) as compared with healthy controls." (PMID 37445827, 2023). "Additionally, MMP-9 levels and MMP-9/TIMP-1 ratio were negatively correlated with endothelium-dependent response in obese and metabolic syndrome people." (PMID 34625635, 2021). "Circulating levels of TIMP-1 and -2 are increased in patients with metabolic syndrome and T2D." (PMID 31581657, 2019). "Since the concentrations of MMP-2 and MMP-9 are higher in patients with the metabolic syndrome and TIMP-1 is significantly higher in obese patients, we assumed that the higher concentrations of the analyzed markers are the consequence rather than the cause of cardiometabolic complications." (PMID 30245717, 2018). "TIMP-1 may represent a novel pharmacological target for improving hepatic insulin sensitivity in patients with the metabolic syndrome, NASH and Type 2 diabetes." (PMID 26168159, 2015). "Interestingly, similar to what we have found in our case, patients with metabolic syndrome also display increased circulating concentrations of pro-MMP-9, MMP-8, and TIMP-1, which were associated with increased concentrations of pro-inflammatory mediators and adhesion molecules." (PMID 20161799, 2010). "MMP-3 levels and MMP-3/TIMP-1 ratio were positively correlated with systolic blood pressure (SBP) or diastolic blood pressure (DBP) in obese and metabolic syndrome people." (PMID 34625635, 2021). "Levels of MMP2, MMP9, TIMP-1 and TIMP-2 are all increased in diabetic patients with dyslipidemia or with acute coronary syndrome." (PMID 25204377, 2014). "We find that individuals having metabolic syndrome in Non-DM and in Pre-DM group have a significantly higher (P < 0.05) level of sTNFRII, sICAM-1, and TIMP-1." (PMID 31178745, 2019). "The aim of this study is to investigate the plasma levels of MMP-1, MMP-2, MMP-3, MMP-9, TIMP-1, TIMP-2 and their ratios in a large variety of study groups including overweight people and obese people with or without metabolic syndrome and non-obese healthy people with total of 479 participants." (PMID 34625635, 2021).
breast tumor (15 papers, 1995 to 2026). "Statistical analyses were performed using R. Results:TIMP1 was the only inhibitor overexpressed in breast tumors and showed significant associations with the Luminal B, HER2, TNBC, and normal-like subtypes, along with a modest increase across stages." (PMID 41718391, 2026). "Overexpression of MMP-2 and under-expression of TIMP-1 were associated with more invasive behavior in breast tumor cells." (PMID 31582999, 2019). "In this study, levels of two MMPs, i.e. MMP-8 and -9, and their inhibitor tissue inhibitor of metalloprotease type 1 (TIMP-1) were measured by enzyme-linked immunosorbent assay in human breast tumours." (PMID 7734294, 1995). "This study is devoted to investigate the clinical significance of IL-12 expression in BC and to deduce its correlation with CA15-3, CEA, MMP9, TIMP1 as breast tumor markers." (PMID 27275301, 2015). "Logistic regression analysis of IHC results for the breast tumors showed that the association between NOS2 and pAkt-(ser473) was strongest in tumors with elevated TIMP-1 protein but reduced in those with low TIMP-1 expression." (PMID 22957045, 2012). "A substantial discordance in ER and HER2 status between primary and metastatic tumor tissue has been reported, and a study has demonstrated differences in the immunoreactivity of TIMP-1 in primary breast tumor tissue and the corresponding axillary lymph node metastasis." (PMID 24884504, 2014). "Thus, the data show that elevated TIMP-1 augments NO-mediated phosphorylation of Akt at ser473 in these breast tumors." (PMID 22957045, 2012). "While several studies have linked TIMP-1 with Akt activation and pro-survival signaling in vitro, this is the first study, to the best of our knowledge, correlating TIMP-1-dependent Akt activation in human breast tumors with poor patient survival." (PMID 22957045, 2012). "TIMP-1 and CD63 exhibited moderate to strong expression in 42% and 41%, respectively, of the breast tumors (respectively)." (PMID 22957045, 2012). "This is in accordance with a previous study where comparison of plasma TIMP-1 with TIMP-1 protein levels in tumor extracts from primary breast tumor patients, revealed a non-significant correlation." (PMID 27619981, 2016). "Because TIMP-1 mediates Akt signaling and is also regulated by NO we explored the relationship between TIMP-l, NOS2, and Akt phosphorylation signaling in the same breast tumors." (PMID 22957045, 2012). "Thus, TIMP-1 constitutes an additional marker of tumor aggressiveness and poor disease outcome for which NOS2 correlates in these breast tumors." (PMID 22957045, 2012).
chronic obstructive pulmonary disease (15 papers, 2011 to 2023). A chronic and progressive lung disorder characterized by the loss of elasticity of the bronchial tree and the air sacs, destruction of the air sacs wall, thickening of the bronchial wall, and mucous accumulation in the bronchial tree. "The MMP-9/TIMP-1 imbalance is associated with multiple disorders such as autoimmune diseases, chronic obstructive pulmonary disease exacerbations and blood-brain barrier disruption." (PMID 34571700, 2021). "Induction of Timp1 has also been implicated in the pathogenesis of other allergic conditions including atopic dermatitis, allergic contact dermatitis and chronic obstructive pulmonary disease (COPD)." (PMID 21211037, 2011). "It has been shown that TIMP-1 levels are elevated in chronic obstructive pulmonary disease and that its elevated levels can lead to increased neutrophil numbers and decreased lung function." (PMID 35141140, 2021). "The present study aims to investigate the effect of Liuweibuqi (LWBQ) capsules on the expression of matrix metalloproteinase (MMP)-9 and TIMP1 and cell viability of alveolar macrophages (AMs) in chronic obstructive pulmonary disease (COPD)." (PMID 28831024, 2017). "The aim of this study was to evaluate serum levels of both MMP-9 and TIMP-1 in COPD patients and to assess their relationship with lung function, symptom severity scores and acute exacerbations of chronic obstructive pulmonary disease (AECOPD)." (PMID 36935521, 2023).
type 2 diabetes (15 papers, 2007 to 2025). "Hepatic Timp1 expression is also elevated in a mouse model that resembles type 2 diabetes, elicited by HFD combined with low doses of strepzotocin treatment in order to induce beta cell dysfunction." (PMID 26168159, 2015). "TIMP-1 expression in Type 2 diabetes LDL treated cells was significantly higher compared to control LDL treated cells for at 4 hours at high LDL concentrations." (PMID 17714581, 2007). "TIMP1 expression is elevated in bone tissue in type 2 diabetes." (PMID 39578773, 2024). "In vivo, TIMP1 knockout reduces the severity of type 2 diabetes-induced osteoporosis." (PMID 39578773, 2024). "Fluorofenidone inhibited TIMP-1 expression in the renal cortex from db/db mice (type 2 diabetes)." (PMID 32046355, 2020). "MMP-10 and TIMP-1 are increased from the early stages of type 2 diabetes." (PMID 31913319, 2020). "Human type 2 diabetes patients exhibited increased plasma levels of TIMP1 and TIMP235." (PMID 27126782, 2016). "In hypercholesterolemic patients with type 2 diabetes, elevated MMP-7 and MMP-8 concentrations were reduced by atorvastatin, along with their ratios to TIMP-1, through suppression of inflammatory mediators." (PMID 39200884, 2024). "Moreover, the study found that MMP-14 and TIMP-1 expression levels were elevated in inflamed gingival tissue, suggesting that PGE2 and MMP-14 may contribute to the process of alveolar bone resorption and the progression of periodontal inflammation associated with type 2 diabetes." (PMID 40075856, 2025). "MMP-10 and TIMP-1 have been implicated in T1DM however, to the best of our knowledge, no previous studies have analysed the role of MMP-10 in type 2 diabetes (T2DM), while TIMP-1 data is not conclusive." (PMID 31913319, 2020).
acute coronary syndrome (14 papers, 2009 to 2026). Signs and symptoms related to acute ischemia of the myocardium secondary to coronary artery disease. "High MMP-8 and tissue-inhibitor of matrix metalloproteinase-1 (TIMP-1) levels are implicated in acute coronary syndrome (ACS)." (PMID 28278213, 2017). "In patients with acute coronary syndrome, elevated plasma levels of MMP-9 and TIMP-1 indicate ongoing plaque rupture and an increased risk of subsequent cardiovascular events." (PMID 39200884, 2024). "The results demonstrated an increase in plasma levels of MMP-9 and TIMP-1 during acute coronary syndromes." (PMID 38254696, 2024). "Increased plasma MMP-9 and TIMP-1 levels have been demonstrated in the coronary circulation in patients with acute coronary syndrome (ACS), which suggests active process of plaque rupture and future risk of cardiovascular events." (PMID 32486345, 2020). "The balance between MMP-9 and endogenous inhibitor, tissue inhibitors of matrix metalloproteinase 1 (TIMP-1), is important in acute coronary syndrome (ACS)." (PMID 29349668, 2018). "Elevated levels of MMP-9 may be linked to plaque rupture and a fatal acute coronary syndrome (ACS) event, especially if this co-occurs with low TIMP-1 levels, which play a role of natural MMP inhibitor." (PMID 40002748, 2025). "It was shown that serum MMP-9 and the MMP-9/TIMP-1 molar ratio may be valuable in acute coronary syndrome (ACS) diagnosis and prognosis." (PMID 32486345, 2020). "It has been observed that ox-LDLs upregulate MMP-9 expression and reduce TIMP-1 expression in monocyte-derived macrophages and that MDA, which is included in TBARS, is correlated with the MMP-9 activity in subjects with acute coronary syndrome." (PMID 25114377, 2014). "The deceased were older, had more manifest acute coronary syndrome (ACS), a lower left ventricular ejection fraction (LVEF), and an estimated glomerular filtration rate (eGFR), but significantly higher MMP13, TIMP-1, hs-CRP, and NT-proBNP compared with the survivors." (PMID 38162139, 2023).